UGT1A1 (UDP glucuronosyltransferase family 1 member A1)
Diseases named in the same sentence as UGT1A1 in open-access papers (continued):
Sharing a sentence is not in itself a finding about the gene and the disease.
Hyperbilirubinemia (continued). "Therefore, it can be concluded that despite being particularly frequent in East Asian population, UGT1A1*6, does not contribute to the development and/or severity of hyperbilirubinemia." (PMID 29534743, 2018). "However, a correlation of GA at nt211 in UGT1A1 with neonatal hyperbilirubinemia was not noted in Caucasian population." (PMID 27557546, 2016). "Although the UGT1A1*6 genotype was not evaluated in the UGT1A1*1 and UGT1A1*28 mouse models, these mechanisms explained the additive role of UGT1A1 gene variations and breastfeeding in significant neonatal hyperbilirubinemia." (PMID 26146841, 2015). "However, to further validate the efficacy of AAT in improving hepatocyte transplantation, the Gunn rat model may be particularly useful, in which a naturally occurring single guanosine base deletion within the UGT1A1 gene results in a lack of enzyme activity and severe hyperbilirubinemia." (PMID 30820592, 2019). "Furthermore, the genetic basis, especially the combined effects of UGT1A1 and SLCO1B genes for unconjugated hyperbilirubinemia in Chinese descendants has not been fully illuminated." (PMID 31737051, 2019).
Gilbert syndrome (152 papers, 2004 to 2026). An autosomal recessive inherited disorder characterized by unconjugated hyperbilirubinemia, resulting in harmless intermittent jaundice. "Patients with Gilbert’s syndrome, caused by a polymorphism in the promoter of UGT1A1, have a reduction in UGT1A1 protein expression, leading to an increase in plasma bilirubin." (PMID 41300483, 2025). "Without genotyping or more detailed clinical characterization, it is difficult to determine the extent to which genetic variants (e.g., UGT1A1 polymorphisms associated with Gilbert's syndrome) contributed to the observed group differences." (PMID 40342636, 2025). "Mice with hyperbilirubinemia due to the human UGT1A1*28 Gilbert’s syndrome polymorphism fed a high-fat diet had significantly lesser hepatic fat accumulation, reduced plasma cholesterol, insulin, and glucose sensitivity." (PMID 40985048, 2025). "Gilbert Syndrome is caused by a homozygous polymorphism in the UGT1A1 gene promoter, leading to decreased hepatic glucuronidation and bilirubin excretion." (PMID 41300483, 2025). "Gilbert’s syndrome (GS) is a common genetic disorder marked by elevated bilirubin levels due to UGT1A1 enzyme deficiency." (PMID 40904555, 2025). "UGT1A1*28 and UGT1A1*37 are common reduced-function alleles associated with Gilbert’s syndrome, drug toxicities, and the discontinuation of drug treatments." (PMID 40870019, 2025). "Gilbert’s syndrome is caused by a genetic mutation that reduces activity of the enzyme UDP glucuronosyltransferase 1 polypeptide A1 (UGT1A1), causing elevated levels of unconjugated bilirubin in the blood and duodenal bile." (PMID 38956524, 2024). "UDP-glucuronosyltransferase (UGT1A1) gene variants (Gilbert syndrome) predispose to jaundice and the formation of gallstones." (PMID 39062234, 2024). "CNS is related to Gilbert syndrome (GS): they are both genetic disorders caused by mutations in the UGT1A1 gene, which affects bilirubin metabolism." (PMID 39456788, 2024). "UGT1A1 gene mutations are the molecular genetic basis for Gilbert syndrome (GS) and Crigler-Najjar syndrome (CNS)." (PMID 38561707, 2024). "In Caucasians, Gilbert ́s syndrome is caused by the UGT1A1*28 polymorphism (the A(TA)7TAA variation of the promoter of the UGT1A1 gene (OMIM*191740), rs8175347) that substantially reduces the glucuronosylation of bilirubin." (PMID 37445792, 2023). "All patients analyzed (n = 12/14) showed the homozygous UGT1A1 promotor variant c.-41_-40dup also known as the A(TA)7TAA or UGT1A1*28 allele, which is associated with the Gilbert syndrome." (PMID 37761392, 2023). "Gilbert syndrome is a common inherited condition association with mutations in the hepatic isoform (1A1) of uridine diphosphoglucose glucuronosyltransferase 1 (UGT1A1)." (PMID 37456363, 2023). "A defect in the UGT1A1 enzyme-encoding gene, which is directly responsible for bilirubin conjugation, can cause Crigler–Najjar syndrome (CNS) and Gilbert’s syndrome." (PMID 37759499, 2023). "While other associated risk alleles have been described, e.g. UGT1A1*6 (rs4148323) in Asian populations, UGT1A1*28 is by far the most common cause for the Gilbert’s syndrome in Caucasians and African Americans." (PMID 36639636, 2023). "Gilbert syndrome is a congenital autosomal recessive disorder characterized by mild unconjugated bilirubin metabolism disorder, which is caused by decreased UDP-glucuronosyltransferase 1A1 (UGT1A1) promoter activity." (PMID 37324459, 2023). "Here, we investigated the association of UDP glucuronosyltransferase family 1 member A1 (UGT1A1), the genetic cause of Gilbert syndrome (GS), a common condition of mild unconjugated bilirubinemia, with HBV infection outcomes." (PMID 38028601, 2023). "It is important to note that UGT1A1 homozygosity is only a predisposing factor for Gilbert syndrome, as its penetrance is only 50%, most likely due to the influence of modifier genes and the presence of specific haplotypes with other UGT1A1 genotypes." (PMID 37324459, 2023).
Gilbert syndrome (continued). "Gilbert’s syndrome patients are typically homozygous carriers of the UGT1A1*28 allele, and have lower UGT1A1 gene expression and diminished bilirubin metabolism." (PMID 35149777, 2022). "Increased number of TA repeats in the promoter (UGT1A1*28; a common cause of Gilbert’s syndrome) was found in 12% of the newborns and was associated with lower risk of NH." (PMID 36962413, 2022). "UGT1A1*60 is a common variant located in the promoter region, which is a risk factor for Gilbert syndrome." (PMID 36128448, 2022). "Genetic polymorphism of UGT1A1 is associated with diseases such as Gilbert syndrome (UGT1A1*6/*6), head and neck cancers, colorectal cancer, and coronary artery disease." (PMID 35176049, 2022). "Gilbert’s syndrome is mainly diagnosed through genetic analysis and is primarily detected through a mutation in the promoter region of the UGT1A1 gene." (PMID 36293566, 2022). "The most common genotype of Gilbert’s syndrome is the homozygous, A (TA)7TAA *28 allele in the promoter of the UGT1A1 gene, reducing the metabolism of bilirubin and causing an accumulation of unconjugated bilirubin in the blood." (PMID 35062878, 2022). "Other variants have been identified that influence UGT1A1 function and are associated with Gilbert’s syndrome but are less common than the UGT1A1*28 allele." (PMID 35149777, 2022). "Genetic variation in UGT1A1 has been linked to Gilbert’s syndrome, a common benign condition characterized by elevations in unconjugated bilirubin and jaundice in the absence of aminotransferase elevations." (PMID 35149777, 2022). "UGT1A1*28 polymorphism was found to be the main cause of Gilbert syndrome which is identified with chronic hyperbilirubinemia." (PMID 35629166, 2022). "Due to the strong linkage disequilibrium between the rs4148325 variant and the UGT1A1*28 allele (r2 = 0.88 and D′ = 0.98), the majority of rs4148325 TT homozygotes likely have Gilbert’s syndrome, with lower gene expression and diminished bilirubin metabolism." (PMID 35149777, 2022). "Another UGT1A1 variant, linked to decreased irinotecan metabolism is UGT1A1*28 or rs8175347 and the pertinent variant is also linked to Gilbert syndrome characterized by periods of intermittent icterus." (PMID 35197553, 2022). "Another coding sequence variants, UGT1A1*73(c.1091C > T, p.Pro364Leu, rs34946978), has also been reported to be linked to a significant decrease in UGT1A1 enzyme activity and the severity of Gilbert’s syndrome in both Caucasian and Asia populations." (PMID 34074250, 2021). "Patients carrying the homozygous UGT1A1*28 allele (known as Gilbert’s syndrome) have decreased hepatic expression of UGT1A1 enzyme, and a lower initial dose is recommended." (PMID 34722328, 2021). "Gilbert’s syndrome, a genetic cause of benign bilirubin elevations, is caused by a deficiency in UGT1A1." (PMID 33472602, 2021). "The UGT1A1*28 variant is also a common cause of Gilbert Syndrome and Crigler-Najjar Syndrome due to low clearance of bilirubin, a waste product that arises from the destruction of aged or abnormal red blood cells." (PMID 33494365, 2021). "Homozygous carriers of the variants T7/T7 (patients with so called Gilbert’s syndrome) have decreased UGT1A1 expression by approximately 70%." (PMID 35056973, 2021). "For instance, a humanized transgenic UGT1A-SNP mouse model was established almost a decade ago, which harbors the Gilbert Syndrome-associated UGT1A variant haplotype including UGT1A1*28, UGT1A3-66T>C, UGT1A6*2a, and UGT1A7*3." (PMID 33494365, 2021). "UGT1A1 coding region mutations have been linked to Gilbert syndrome in Asian populations, and homozygosity for UGT1A1 is a causative factor for Gilbert’s syndrome." (PMID 32881938, 2020). "UGT1A1 is involved in conjugation of bilirubin and polymorphism of UGT1A1 is associated with Gilbert syndrome." (PMID 32084209, 2020).
Gilbert syndrome (continued). "Congenital underexpression of UGT1A1 causes mild chronic unconjugated hyperbilirubinemia, known as “Gilbert’s syndrome (GS),” and is associated with a polymorphism of the 5′ end of the UGT1A1 gene promoter." (PMID 32878631, 2020). "Polymorphisms in UGT1A1 are associated with indirect bilirubin concentrations in the general population (i.e. Gilbert’s syndrome)." (PMID 30962262, 2019). "Analysis of the (TA) polymorphism in the UGT1A1 gene promotor showed that homozygosity for UGT1A1*28 was the most frequent finding in subjects with Gilbert’s syndrome (Groups A: 97.546% and B: 95.238%; P = 0.6046)." (PMID 30717703, 2019). "The homozygous polymorphism [A(TA)7TAA] in the promoter of the gene for UDP-glucuronosyltransferase 1A1 (UGT1A1) is the most frequent genotype of Gilbert’s syndrome." (PMID 30717703, 2019). "Other mutations occurring in the coding region of UGT1A1 c.686C > A, c.1091C > T and c.1456T > G can also lead to Gilbert syndrome amongst the Asian population." (PMID 31737051, 2019). "In this context, UGT1A1*28 (rs8175347), a TA tandem repeat in the UGT1A1 promoter causing Gilbert syndrome/Morbus Meulengracht is of relevance causing defective heme metabolism." (PMID 35582146, 2019). "The most thoroughly studied variant of UGT1A1 is termed as UGT1A1*28 (rs8175347) and is associated with Gilbert’s syndrome." (PMID 29743555, 2018). "Genetic analysis of the patient also revealed a p.TA7/7 mutation in UGT1A1 indicating Gilbert syndrome." (PMID 29761093, 2018). "The Gilbert's syndrome is characterized by familial unconjugated hyperbilirubinemia, due to UGT1A1 mutations causing defective conjugation of BR with glucuronic acid in the liver." (PMID 29259555, 2017). "For example, a number of mutations in the regulatory and coding regions of the UGT1A1 gene have been detected to confirm the diagnosis of Gilbert's syndrome." (PMID 29376065, 2017). "Upon reactive pathway progression, as in Gilbert’s Syndrome (GS; UGT1A1*28 polymorphism), aggravated health effects have been determined." (PMID 28389660, 2017). "Gilbert’s Syndrome is associated with genetic variations in the UGT1A1 gene promoter region, of which the so-called UGT1A1*28 is the most common among Caucasians." (PMID 26926838, 2016). "A heterozygous genotype UGT1A1⁎28 polymorphism associated with Gilbert's syndrome was also found in this Argentine patient." (PMID 26977326, 2016). "Based on observations that individuals with Gilbert’s syndrome (GS; UGT1A1*28 promoter mutation) are generally lighter, leaner and healthier than controls, specific inter-group differences in the AMPK pathway regulation were explored." (PMID 27444220, 2016). "Healthy carriers of the UGT1A1*28 promoter mutation, that is characteristic for the benign condition of Gilbert’s syndrome (GS; i.e. M. Meulengracht), present with moderate unconjugated hyper-bilirubinaemia." (PMID 27444220, 2016). "The genotype UGT1A1⁎28 associated with Gilbert's syndrome was performed and a heterozygous genotype UGT1A1⁎28 polymorphism was found." (PMID 26977326, 2016). "The UGT1A1 coding sequence variant rs4148323 (known as UGT1A1*6, G211A), the most common cause of Gilbert syndrome in east Asians, was well documented and predominantly associated with TSB levels and neonatal hyperbilirubinemia risk in the Asian population." (PMID 26146841, 2015). "Mutations in UGT1A1 have also been associated with Crigler-Najjar syndromes types I and II and in Gilbert syndrome." (PMID 26628212, 2015). "Genetic variants causing absence, or severe reduction of UGT1A1 activity lead to mild forms of unconjugated hyperbilirubinemia, Gilbert syndrome (GS) and CNS-II, or a severe CNS-I form." (PMID 25319636, 2014). "Both have been studied for many years and causal genes (UGT1A1 for Gilbert's syndrome and VWF for von Willebrand disease) are known." (PMID 25188385, 2014).
Gilbert syndrome (continued). "Gilbert's syndrome is characterized by mildly elevated unconjugated bilirubin, caused by a genetic variant of the UGT1A1 gene on human chromosome 2." (PMID 24690955, 2014). "These mutations have been associated with CNS-II except that p.G71R occurred mostly in Gilbert syndrome (a mild form of hereditary UGT1A1-associated syndromes)." (PMID 25319636, 2014). "The UGT1A1*28 allele, associated with Gilbert's syndrome, has a prevalence of 16% in Europeans, 12% in Indians, 8% in Egyptians, 28% in African–Americans while Chinese and Japanese have low frequencies of the allele." (PMID 23224752, 2013). "It was successfully applied for the genotyping of Factor V Leiden, Gilbert Syndrome UGT1A1 (TA)n promoter polymorphism and for the enrichment and detection of rare alleles." (PMID 24116084, 2013). "Two prevalent UGT1A1 polymorphisms responsible for Gilbert’s syndrome have been identified: G71R in exon 1 and A(TA)7TAA in the TATA box of the promoter region." (PMID 23388413, 2013). "The presence of a polymorphism in the uridine diphosphate glucuronosyltransferase 1A1 (UGT1A1) gene, which predisposes to Gilbert's syndrome, leads to reduced enzymatic activity necessary for the conjugation of bilirubin allowing it to be excreted in bile." (PMID 22007339, 2011). "Further polymorphisms located upstream of the UGT1A1-coding region have recently been detected but, apart from A(TA)7TAA and -3275T>G at gtPBREM, the role of these polymorphisms in the development of Gilbert syndrome is currently unclear." (PMID 20529348, 2010). "Genetic variation in UGT1A1 enzyme was first related to the Gilbert's syndrome, in which the homozygous variant genotype UGT1A1*28/*28 is responsible for a less efficient bilirrubin glucoronidation." (PMID 20628391, 2010). "It is caused by defects of UGT1A1 and is one of the most prevalent congenital metabolic disorders; Gilbert syndrome is found clinically in 3-10% of the population." (PMID 20529348, 2010). "By reducing the transcription of UGT1A1, A(TA)7TAA is acknowledged to be one of the most important causes of Gilbert syndrome." (PMID 20529348, 2010). "UGT1A1 polymorphisms result in reduced UGT1A1 activity giving rise to genetic hyperbilirubinaemic syndromes such as Crigler–Najjar types I & II and Gilbert's syndrome and can lead to reduced gluronidation of SN-38." (PMID 15365570, 2004). "Gilbert syndrome (GS) is a genetic disorder caused by mutations in the UGT1A1 gene." (PMID 41169420, 2025). "In a study involving 100 healthy Caucasians people and 50 Egyptians, researchers investigated the co-occurrence of a TATA box mutation associated with Gilbert’s syndrome (UGT1A1-28) along with other polymorphisms in the UDP-glucuronosyltransferase-1 locus (UGT1A1-6 and UGT1A1-73)." (PMID 40432911, 2025). "However, patients with Gilbert’s syndrome, caused by a polymorphism in the UGT1A1 gene promoter that results in its protein with reduced activity, have a 2–3 fold increase in plasma bilirubin levels and lower cardiovascular risks." (PMID 40985048, 2025). "Mutations in UGT1A1 can cause disorders like Gilbert syndrome and Crigler-Najjar syndrome." (PMID 40432911, 2025). "Individuals with Gilbert's syndrome (GS) exhibit genetic polymorphisms in the region of uridine diphosphate glucuronosyltransferase 1A1 (UGT1A1), causing a 60%–70% reduction in the liver's ability to conjugate bilirubin, and thus leading to substantially higher serum bilirubin levels." (PMID 39425533, 2024). "Some individuals with a poor metabolizer phenotype may be detected due to the presence of Gilbert’s syndrome, an inherited deficiency in UGT1A1 enzyme activity resulting from polymorphisms in the UGT1A1 gene, often involving the *28 allele." (PMID 39682117, 2024). "Moreover, rs6744284 genotypes were strongly linked to the Gilbert’s syndrome-associated UGT1A1*28/*37 allele (r2 = 0.70), providing functional support for study findings." (PMID 36639636, 2023).